BNIP3L (BCL2 interacting protein 3 like)
Diseases named in the same sentence as BNIP3L in open-access papers (continued):
Sharing a sentence is not in itself a finding about the gene and the disease.
tumor (continued). "Interestingly, the ablation of Parkin-independent mitophagy receptors BNIP3 or BNIP3L/NIX exhibits the opposite roles for tumor progression in different spontaneous mouse cancer models." (PMID 38067169, 2023). "Furthermore, we examined TET2, BNIP3, and BNIP3L protein levels in HCC-SR tumour tissues by performing immunohistochemical staining." (PMID 37005657, 2023). "In both Gpr176−CKO mice model and the subcutaneous tumor model, loss of GPR176 significantly diminished BNIP3L phosphorylation, while a slight alteration in PINK1 phosphorylation level was observed, suggesting that GPR176 mainly modulated BNIP3L phosphorylation both in vitro and in vivo." (PMID 36905238, 2023). "MenSC treatment increased the levels of TET2, BNIP3, and BNIP3L in the Huh7-SR xenograft tumours." (PMID 37005657, 2023). "BNIP3 and BNIP3L are two BH3 domain-only proteins that have been reported to be associated with cell apoptosis, mitochondrial dysfunction, and mitophagy, and many previous studies have indicated that they are tumour suppressor genes." (PMID 37005657, 2023). "Moreover, BNIP3L/NIX functions as a selective receptor for autophagy that is highly expressed in tumor cells, which is crucial to promote mitophagy under hypoxic TME through NFE2L2/NRF2 transactivation." (PMID 36160153, 2022). "However, a greater amount of evidence from different cancer cell lines and animal models showed BNIP3L-mediated mitophagy alters with the stage of tumor progression." (PMID 34930907, 2021). "Thus, the obtained results demonstrate that under hypoxic conditions, BNIP3 and BNIP3L can rescue tumor cells treated with antitumor drugs by executing mitophagy." (PMID 34439183, 2021). "Our very recent studies highlighted a new hypoxia-induced pathway in which NANOG activates BNIP3L expression, contributing to autophagy induction in hypoxic tumor cells and their resistance to killing by CTL further suggesting a link between hypoxia-induced resistance and autophagy-related stemness." (PMID 29312568, 2017). "Besides mTOR, HIF-1α plays a crucial role by upregulating its targets expression, BNIP3 and BNIP3L, to activate autophagy in tumor cells." (PMID 28729825, 2017). "In addition, transcriptional factor hypoxia-inducible factor 1 subunit alpha (HIF1A/HIF1α)-mediated BNIP3L upregulation is required for hypoxia-induced mitophagy, indicating a potential role of BNIP3L-mediated mitophagy in hypoxic tumor microenvironments (TMEs)." (PMID 33262988, 2020). "In response to low oxygen levels, tumor cells adapt by activating HIF-1 and its downstream target genes, such as BNip3 and BNip3L." (PMID 40129974, 2025). "In mitophagy pathway, a total of seven proteins belonged to Stage I unique up-regulated proteins, among which TFEB, BNIP3L and SP1 were either statistical significantly up-regulated in Stage I when compared to middle and late stage tumor groups." (PMID 38182978, 2024). "In the primary tumor, APLP2, BNIP3L, CD59 and DKK3 were highly expressed in 29.7% (n = 38), 64.9% (n = 83), 92.2% (n = 118) and 80.5% (n = 103), respectively." (PMID 35796776, 2023). "Conversely, BNIP3L/NIX, another mitophagy receptor, stimulates mitophagy in cancer cells, facilitates metabolic demands, and inhibits cell death, thus promoting tumor progression." (PMID 38067169, 2023). "Tumor cells can endure hypoxia through Beclin1-mediated cytoprotective autophagy by upregulating the transcription of BNIP3 and BNIP3L." (PMID 36160153, 2022). "We found that the tumor cells were rescued by receptor-mediated mitophagy involving BNIP3 and BNIP3L proteins." (PMID 34439183, 2021).
tumor (continued). "Significantly higher transcript levels were observed in GBM tumours for AIDA (2.5-fold, p = 3.4 × 10−8), BNIP3L (1.2-fold, p = 5.5 × 10−6), CETN3 (1.8-fold, p = 1.7 × 10−7), FYB1 (1.8-fold, p = 7.25 × 10−9) and POLR2D (1.7-fold, p = 8.14 × 10−5)." (PMID 32635403, 2020). "The other cluster including RASSF5, RASSF6, STAT1, CEACAM1, BNIP3L and SOCS2 is related to tumor suppression." (PMID 32201535, 2020). "Here, selective autophagy in the form of mitophagy-regulated by NIX/BNIP3L- and PINK1-mediated pathways represents a tumor suppressor mechanism, as the elimination of damaged mitochondria prevents the further accumulation of ROS." (PMID 31906235, 2019). "Using global gene expression analysis, we found that a panel of commonly observed hypoxia-inducible genes, including BNIP3L, EGLN3, LOXL4 and P4HA1, were significantly upregulated in the EGFP+ MDA-MB-231 tumor cells, compared to the EGFP− cells." (PMID 29510720, 2018). "In CD133-expressing cells, the percentage of cells with autophagic activity was significantly higher than in all tumor cells, of 68%, 79% and 75% for BECLIN1, BNIP3L, and for LC3B respectively (p < 0.01)." (PMID 28445132, 2017). "We found that CD133-expressing stem-cells had significantly higher mRNA expression levels of BECN1, BNIP3L, MAPLC3B, CAIX and HIF1A than CD133-negative tumor cells (p < 0.05)." (PMID 28445132, 2017). "Nix (also named Bnip3L), which is a mitochondrial outer membrane protein, is the BH3-only member of the Bcl-2 family that inhibits the proliferation of tumor cell lines." (PMID 25689426, 2015). "Previous reports indicate that the NIX/BNIP3L gene acts as a pro-apoptotic factor by interacting with BCL2 and BCL-XL, playing an important role in hypoxia-dependent cell death and acting as a tumor suppressor." (PMID 22984526, 2012). "The immunoreactivity of the BNIP3L and PTPN14 staining was strong in the primary tumour (score 3), whereas weak staining was observed in the liver metastases (score 1)." (PMID 17940512, 2007). "BNIP3L/NIX-mediated mitophagy was first described in developing reticulocytes and has been identified in neurons, renal cells, retinal ganglion cells, and several types of tumor cells." (PMID 36750550, 2023). "Oncogenic KRas induces BNIP3L/NIX expression, highlighting its role in mitophagy induction and PDAC progression; however, direct evidence for mitophagy activity and mitochondrial levels during tumor progression remains limited." (PMID 38067169, 2023). "Furthermore, oxidative stress in tumor cells induces the activation of pro-autophagy factors, such as LC3, BNIP3L, ATG16L, BNIP3, NF-κB, and HIF-1α, which promote the degradation of caveolin-1 (Cav-1), leading to autophagy activation." (PMID 32707662, 2020). "As HIF-1α induces the expression of genes related with tumor survival, we assessed the mRNA levels of CCND2, VEGF, BNIP3L, and CA9, and found that CCND2, VEGF, BNIP3L, and CA9 were upregulated when spheroids were treated with OA, whereas their mRNA levels decreased upon FABP5 or HIF-1α silencing." (PMID 33128030, 2020). "Interestingly, AIDA, BNIP3L, CETN3, FYB1 and POLR2D were specific to GBM plasma-EV, and correspondingly, significantly higher gene expression levels were observed in GBM tumour tissue relative to healthy brain." (PMID 32635403, 2020). "Importantly, decreased levels of mitophagy-related BNIP3L and PINK1, as well as increased levels of mitochondrial biogenesis related genes PPARGC1A and PPARGC1B were found in the basal-like tumor samples when compared to the Luminal A subtype." (PMID 31231612, 2019). "When all tumor cells were counted, numbers of BECLIN1 expressing cells, BNIP3L expressing cells, and LC3B expressing cells were significantly smaller in pCR patients than in non-pCR patients (1.1% vs. 5.8%, 8.5% vs. 18%, and 3.6% vs. 12% respectively, p < 0.05)." (PMID 28445132, 2017).
tumor (continued). "However, sorafenib resistance in HCCLM3-SR cells (low endogenous expression of BNIP3/BNIP3L) was not reversed by MenSCs, suggesting that the crosstalk between MSCs and tumour cells is also affected by intertumour heterogeneity." (PMID 37005657, 2023). "In the present study, the three markers from the fibrosome with the highest reported predictive values (APLP2, BNIP3L, CD59) and an additional well-known fibrosis marker (DKK3) in renal and cardiac disease were investigated on protein expression level in primary tumor samples." (PMID 35796776, 2023). "Interestingly, some of them function as tumor suppressors (e.g. BCL2L11, MXD1, WWOX, BNIP3L, and DMTF1) or are candidate tumor suppressors having anti-proliferative properties and DNA repair abilities (e.g. LRRC2, RPA4, PPP6R1, SPEN, RAP1GAP and CISH) (see discussion section)." (PMID 26918450, 2016). "Inhibition of miR-30a induced significant upregulation of BNIP3L, PRDM9, and SEPT7, while inhibition of miR-934 increased the expression of HIPK2, HOXA4, and MLL3, suggesting that the miRNAs exert negative regulatory effects on these established tumor suppressors." (PMID 26472042, 2015). "Still, the research is short of mechanistic explanation on the regulation of LBX2-AS1 on FOXOA1 and BNIP3L/NIX, and the potential mechanism of FOXO3A downregulating mitophagy and protecting tumor cells was not completely elaborated." (PMID 38326905, 2024). "In addition, hypoxia promotes PDGFR-induced autophagy in tumor cells dependent on HIF-1α signaling while independent of BNIP3 and BNIP3L." (PMID 28729825, 2017).
cancer (52 papers, 2003 to 2025). A tumor composed of atypical neoplastic, often pleomorphic cells that invade other tissues. "BNIP3L has been implicated in a variety of human diseases, including cancer, neurological, metabolic, and cardiovascular disorders." (PMID 34930907, 2021). "To clarify the role of BNIP3L-dependent mitophagy in cancer stemness caused by HBx-expressing, we selected MHCC-97H cells with a high proportion of SP cells to construct a mitophagy inhibition model by using siBNIP3L." (PMID 32168902, 2020). "Furthermore, it is now clear that problems in BNIP3L-mediated mitophagy are associated with a number of human diseases, including neurological disorders, metabolic diseases, and cancer." (PMID 34930907, 2021). "We then explored the methylation levels (beta-values, HumanMethylation450) of MAP1LC3A, OPTN, PINK1, PRKN, SRC, BNIP3L, and BECN1 in pan-cancer and their association with gene expression and the immune cell infiltrates." (PMID 39859167, 2025). "Briefly, we employed a BNIP3(L)-promoter-eGFP-reporter system to isolate cancer cells with high BNIP3/BNIP3L transcriptional activity by flow cytometry (FACS)." (PMID 38834039, 2024). "Receptor‐mediated mitophagy, which involves proteins such as FUNDC1, BBNIP3, and BNIP3L/NIX, is associated with treatment in cancer cells and prognosis." (PMID 38334464, 2024). "BNIP3 silencing by DNA methylation is a common event in many types of cancers, and a clinical investigation suggested that the methylation frequency in the BNIP3 and BNIP3L promoters is associated with a poor prognosis for patients with HCC." (PMID 37005657, 2023). "Both the BNIP3 and BNIP3L promoter regions contain CpG islands, and downregulation of BNIP3 and BNIP3L is always accompanied by promoter methylation in different cancer types." (PMID 37005657, 2023). "Taken together, BNIP3L-mediated autophagy/mitophagy plays a complex role in the fate of cancer cells." (PMID 34930907, 2021). "Several studies showed BNIP3L is involved in diseases such as cancer, neurodegenerative disorders, and acute brain injury." (PMID 34930907, 2021). "In AML cells, Bnip3l silencing leading to increased sensitivity to mitochondria- but not DNA-targeting drugs, also implies a potential link between BNIP3L-mediated mitophagy and cancer cell survival." (PMID 34930907, 2021). "We further discuss current evidence indicating the involvement of BNIP3L-mediated mitophagy in human disease, particularly in cancer and neurological disorders." (PMID 34930907, 2021). "Compared with HBx-expressing Huh7 cells, the expression of cancer stemness and BNIP3L-dependent mitophagy-related proteins was decreased in HBx-expressing Huh7 cells treated with antagonistic anti-HBx." (PMID 32168902, 2020). "BNIP3L-dependent mitophagy and reverse Warburg effect was induced in CAFs through the uptake of cancer cell-derived exosomal ITGB4." (PMID 32957712, 2020). "In summary, we proposed a positive feedback loop, in which HBx induced BNIP3L-dependent mitophagy which upregulated glycolytic metabolism, increasing cancer stemness of HCC cells in vivo and in vitro." (PMID 32168902, 2020). "In summary, we proposed a positive feedback loop, in which HBx-expression induced BNIP3L-dependent mitophagy which upregulated glycolytic metabolism reprogramming, increasing cancer stemness of HCC cells in vivo and in vitro." (PMID 32168902, 2020). "Hypoxia-induced autophagy via BNIP3 and BNIP3L has been described as a stress-survival mechanism in mouse embryonic fibroblasts and various cancer cell lines to promote cancer progression." (PMID 29263786, 2017). "Indeed, cancer cells sustain hypoxia by upregulating the BCL2 interacting protein 3 (BNIP3)/BNIP3-like (BNIP3L), which in turn induces Beclin-1 dependent autophagy by destabilizing Bcl-2-Beclin-1 complex." (PMID 40917756, 2025).
cancer (continued). "Moreover, it has been reported that cancer cells sustain hypoxia by upregulating the BCL2 interacting protein 3 (BNIP3)/BNIP3-like (BNIP3L), which in turn induces BECLIN-1 dependent autophagy by destabilizing Bcl-2-BECLIN-1 complex." (PMID 40917756, 2025). "Furthermore, cancer cells with increased BNIP3/BNIP3L transcriptional activity exhibited CSC features, such as greater mammosphere-forming ability and high CD44 levels." (PMID 38834039, 2024). "However, current evidence supports BNIP3L is involved in a variety of human diseases, from cancer to neurological disorders." (PMID 34930907, 2021). "In a variety of cancer cell lines, BNIP3L regulation triggers autophagy and decreases cell death." (PMID 34930907, 2021). "The contribution of BNIP3L to cancer cells remains controversial." (PMID 34930907, 2021). "We also noted that BNIP3L-mediated mitophagy might play a role in anti-cancer treatment by regulating the formation of immunological memory." (PMID 34930907, 2021). "BNIP3L plays a dual role in different kinds of cancer progression." (PMID 34930907, 2021). "BNIP3L (Bcl2 and adenovirus E1B 19-kDa-interacting protein 3-like), also known as NIX, are the proteins which interact with Bcl2 and are involved in cell death and autophagy, suggesting that BNIP3L/NIX are implicated in the pathogenesis of cancer." (PMID 30669284, 2019). "Also, mitophagy was reported to be impaired in cancer cachexia, as shown by the observation that Bnip3L and Parkin1 mRNA increased in the muscle of cancer patients." (PMID 29785246, 2018). "Hence, it is still a pending question whether disturbing BNIP3L-mediated mitophagy represents a safe and efficient strategy in cancer therapy." (PMID 34930907, 2021). "The analysis of CNVs in PRKN, OPTN, PINK1, SRC, BNIP3L, BECN1, and MAP1LC3A across various cancer types revealed significant heterogeneity in the types and frequencies of CNVs." (PMID 39859167, 2025). "Overall, the Spearman’s correlation coefficients varied across different cancer types, revealing distinct patterns of immune cell correlation with the expression of OPTN, PINK1, MAP1LC3A, PRKN, BNIP3L, BECN1, and SRC." (PMID 39859167, 2025). "We delved into the molecular mechanisms by which LC3, PINK1, PRKN, SRC, BNIP3L, BECN1, and OPTN regulate mitophagy, cancer progression and drug sensitivity or resistance." (PMID 39859167, 2025). "Last, we gathered the IC50s of a wide variety of drugs among different cancer cell lines through the GDSC and CTRP databases and assessed the relationship between the mRNA values of MAP1LC3A, OPTN, SRC, BNIP3L, BECN1, PINK1, and PRKN and drug sensitivity." (PMID 39859167, 2025). "Heterozygous deletions were prevalent in PRKN, BNIP3L, OPTN, and PINK1, particularly in cancers such as LUSC, ESCA, HNSC, and COAD." (PMID 39859167, 2025). "In cancer, it inhibits the growth of cancer cells by inducing the expression of Foxo3 and inhibiting telomerase reverse transcriptase mRNA to activate mitochondrial-related proteins BNIP3 and BNIP3L." (PMID 38474452, 2024). "Herein, we describe a new model system to enrich sub-populations of cancer cells with high basal levels of mitophagy, based on the functional transcriptional activity of BNIP3 and BNIP3L." (PMID 38834039, 2024). "Dysregulation of mitophagy-related proteins, such as FUNDC1, Parkin, BNIP3, BNIP3L/NIX, and p62/SQSTM1, has been shown to be correlated with cancer." (PMID 39524226, 2024). "The corresponding heatmap analysis also indicated a positive correlation between P4HA1 and these five genes (BNIP3L, FUT11, LDHA, PGK1, and RPL17P50) in the majority of 32 types of cancers." (PMID 35812752, 2022). "Cancer-derived EVs transfer ITGB4 and induce BCL2 interacting protein 3 like (BNIP3L)-dependent mitophagy and glycolysis in CAFs." (PMID 36424598, 2022).